C5 (complement C5)
Diseases named in the same sentence as C5 in open-access papers (continued):
Sharing a sentence is not in itself a finding about the gene and the disease.
bacterial meningitis (2 papers, 2015 to 2019). Inflammation of the membranes surrounding the brain and spinal cord due to a bacterial infection. "The effect of anti-C5 antibody treatment in bacterial meningitis caused by pathogens other than S. pneumoniae is unclear and should be studied separately." (PMID 26272468, 2015). "However, treatment with C5 antibodies blocks the terminal complement pathway impairing the killing of Neisseria meningitidis, the second most common cause of bacterial meningitis." (PMID 31883521, 2019).
cardiomyopathy (2 papers, 2019 to 2020). A disease of the heart muscle or myocardium proper. "This has ushered in a new treatment paradigm of TMA‐associated cardiomyopathy with C5 inhibitor eculizumab in addition to traditional use of anticoagulation, corticosteroids, plasma exchange, and IVIG." (PMID 35847716, 2020). "Interestingly, it was recently reported that DYSF deficiency leads to increased susceptibility to coxsackievirus B3 (CB3)-induced cardiomyopathy in C5-deficient A/J mice and suggested an important mechanism of DYSF cleavage by viral proteases underpinning cardiac dysfunction." (PMID 31601172, 2019).
cataract (2 papers, 2017 to 2024). Partial or complete opacity of the crystalline lens of one or both eyes that decreases visual acuity and eventually results in blindness. "The ratios of aqueous humour/plasma of C1q, C4, C4b, C3b/iC3b, C5, CFB, CFD, CFI, and CFH in the RVO patients were significantly higher than those in the cataract patients." (PMID 39587546, 2024). "It is worth noting that C3b/iC3b but not C5a was detected in the aqueous humour of cataract patients and the intraocular level of C5a did not correlate with C3b/iC3b in RVO patients, suggesting that C3 cleavage does not necessarily lead to C5 cleavage inside the eye." (PMID 39587546, 2024).
chlamydial infection (2 papers, 2014 to 2021). "These discoveries illuminate the mechanism of a C3-independent C5 activation induced by chlamydial infection, and furthermore provide a potential therapeutic target and drug for preventing tubal fibrosis caused by chlamydial infection." (PMID 35087765, 2021). "The current study aimed to explore the mechanism of C3-independent C5 activation induced by chlamydial infection." (PMID 35087765, 2021). "The results demonstrate a new pattern of C5 activation, and previously unidentified C5 products were induced by chlamydial infection attributed to CPAF, a chlamydial secreted serine protease." (PMID 35087765, 2021). "These discoveries reveal the mechanism of C3-independent C5 activation induced by chlamydial infection, and furthermore provide a potential therapeutic target and drug for preventing tubal fibrosis caused by chlamydial infection." (PMID 35087765, 2021). "NM strongly inhibited C5 activation induced by chlamydial infection." (PMID 35087765, 2021). "Western blot analysis revealed that NM completely blocked the C3-independent C5 activation triggered by different dilutions of C. trachomatis-HeLa229 cell lysates, suggesting that NM had an inhibitory effect on the C5 activation induced by chlamydial infection." (PMID 35087765, 2021). "Thus, the result suggested the middle and late stage of chlamydial infection is closely related to C5 cleavage, and also demonstrated that the invasion of Chlamydia didn’t induce host cells to secrete the new protease that cleave C5." (PMID 35087765, 2021). "It will be interesting to test whether C5 deficiency is responsible for the reduced inflammatory cytokine responses and lack of hydrosalpinx in A/J mice after chlamydial infection." (PMID 24736397, 2014). "This suggested that the process of incubation itself or the presence of HeLa229 cells lysates alone did not produce the C5 cleavage effect, and that cleavage of C5 observed in the C. trachomatis infection group was induced by chlamydial infection." (PMID 35087765, 2021). "A C3-independent C5 activation pathway was previously demonstrated to contribute to tubal fibrosis induced by chlamydial infection, but the mechanism by which chlamydial infection activates C5 in the absence of C3 remains to be elucidated." (PMID 35087765, 2021). "However, the mechanism of how chlamydial infection activates C5 in the absence of C3 has yet to be elucidated." (PMID 35087765, 2021). "However, it is not known how chlamydial infection activates C5 in the absence of C3." (PMID 35087765, 2021). "This combination of results indicated that CPAF participated in a C3-independent C5 activation during chlamydial infection, but not distinguished between the two possibilities: 1) CPAF directly cleaved C5." (PMID 35087765, 2021).
coagulation disorder (2 papers, 2015 to 2017). "In the present study, histone-induced lethal thrombosis and the coagulation disorder were milder in C5-deficient mice than in C5-sufficient mice." (PMID 28205538, 2017).
colitis (2 papers, 2016 to 2021). Inflammation of the colon. "C5 deficiency in an earlier study was also shown to make mice more susceptible to colitis after 10 days, supporting this protective role." (PMID 33692968, 2021). "Complement activation also contributed to the development of colitis-associated colorectal cancer (CAC), supported by tumor repression in complement deficient mice (C3, C5, or C5aR)." (PMID 33692968, 2021). "Many of the inflammatory cytokines attenuated by FFAR2 and FFAR3, including C5, CCL1, CCL2, GM-CSF, IL-1α, IL-1β, ICAM-1 and TNF, are associated with colitis." (PMID 27667443, 2016).
colon cancer (2 papers, 2020 to 2021). "Colon tumors (or counterpart tissues in C5- or C5ar1-deficient mice), spleen and blood samples were collected from mice for profiling immunocytes by flow cytometry or IHC assay." (PMID 32754267, 2020).
cryptococcal infection (2 papers, 2015 to 2021). "(in vivo) Cryptococcus neoformans infection model in mice (WT, C3 deficient, and C5 deficient)." (PMID 34408631, 2021). "Another complement protein, C5 is also implicated, with mice strains more susceptible to cryptococcal infection when C5 was not present in their plasma." (PMID 25498576, 2015).
diabetes (2 papers, 2018 to 2025). "The complement system, specifically C5, has been implicated in a wide range of pathologies—including Alzheimer's, retinopathies, diabetes, autoimmune disorders, and classical diseases of “complement” such as atypical hemolytic uremic syndrome (aHUS)." (PMID 41189475, 2025). "In addition to their roles in innate immunity, an emerging body of literature suggests that intact C3 and C5 complement proteins, and the cleaved C3a and C5a peptides, are important in regulating whole body metabolism, energy homeostasis and the pathogenesis of diabetes and metabolic syndrome." (PMID 28921001, 2018).
diabetic nephropathy (2 papers, 2019 to 2023). "Specifically in diabetic nephropathy, we here identified a positive association between SGLT-2 expression and the tubulointerstitial synthesis of the complement component C5." (PMID 38069385, 2023). "In diabetic nephropathy, we identified positive correlations specifically with complement components C2 and C5 and receptors C5AR2 and CR2." (PMID 38069385, 2023). "Furthermore, tubulointerstitial SGLT-2 correlated explicitly with the tubulointerstitial synthesis of complement component C5 in diabetic nephropathy." (PMID 38069385, 2023). "Moreover, there is evidence for a pivotal role of the complement component C5 and its anaphylatoxin C5a signaling axis in contributing to kidney injury in experimental diabetic nephropathy." (PMID 38069385, 2023).
diabetic proliferative retinopathy (2 papers, 2016 to 2018). "In addition, whether other non-diabetic proliferative retinopathy including central retinal vein occlusion (CRVO), rhegmatogenous retinal detachment, ocular penetrating injury showed an association with C5 polymorphisms remains unclear and future study needs to be investigated." (PMID 26934706, 2016).
diabetic retinopathy (2 papers, 2017 to 2018). "Another study found a weak association between the coding SNP rs17611 (which results in the V802I polymorphism in the C5 protein previously associated with rheumatoid arthritis) and diabetic retinopathy in type 2 diabetes." (PMID 28948331, 2018). "There have been recent genetic association studies linking the C5 gene with diabetic retinopathy." (PMID 28948331, 2018). "In diabetic retinopathy 34 genes including AP15, GRB2, IL17A, PLXDC1, C5 and L1CAM were studied in a single year in which, C5 and L1CAM are reported as recently as in 2016." (PMID 28761062, 2017).
E. coli infection (2 papers, 2016 to 2025). "We found that lnc-ANKRD37-1, lnc-CDC6-3, lnc-C5-1, lnc-BIRC3-1 and lnc-RP11-582J16.5.1-2 were upregulated in all of these three cell lines (by ≥2-fold), but exhibited responses of various intensities to meningitic E. coli infection." (PMID 27958323, 2016).
endometriosis (2 papers, 2025). The growth of functional endometrial tissue in anatomic sites outside the uterine body. "Increased amounts of C1, C3, and C5 were detected in serum and peritoneal fluid of women with endometriosis." (PMID 40698088, 2025). "Higher amounts of C1, C3, and C5 have been detected in serum and peritoneal fluid of women with endometriosis." (PMID 40698088, 2025).
gastroenteritis (2 papers, 2025 to 2026). An inflammatory disorder that affects the upper and lower gastrointestinal tract. "Complement is a double-edged regulator of inflammation in IBD, with C1q, CD46, CD55, CD59, and C6 emerging as protective against intestinal inflammation, while C3, C5, and C5a amplify mucosal injury via pro-inflammatory cascades." (PMID 41252181, 2026).
gout (2 papers, 2024). A condition characterized by painful swelling of the joints, which is caused by deposition of urate crystals. "These novel biomarkers of XOI treatment effects were identified within an interactome with central gout mediators including IL-1B, CXCL8, IL6, and C5." (PMID 39426967, 2024).
hereditary angioedema (2 papers, 2020). Hereditary angioedema (HAE) is a genetic disease characterized by the occurrence of transitory and recurrent subcutaneous and/or submucosal edemas resulting in swelling and/or abdominal pain. "Two complement drugs, C1 esterase inhibitor (C1-INH) and the anti-C5 antibody drug eculizumab/Soliris, have reached market, although C1-INH is FDA-approved for an indication not primarily mediated by complement (hereditary angioedema (HAE))." (PMID 32899120, 2020).
hypertensive emergency (2 papers, 2025 to 2026). "Although C5 inhibitors, such as eculizumab and ravulizumab, have markedly improved outcomes, renal recovery remains limited in cases complicated by hypertensive emergency (HE) or malignant hypertension, likely due to complement-independent vascular injury." (PMID 41680667, 2026).
ischemia (2 papers, 2020 to 2022). A hypoperfusion of the BLOOD through an organ or tissue caused by a PATHOLOGIC CONSTRICTION or obstruction of its BLOOD VESSELS, or an absence of BLOOD CIRCULATION. "Activated C5 complement components are a part of the cerebral tissue inflammation following ischemia." (PMID 36825211, 2022).
leukemia (2 papers, 2019 to 2024). A malignant (clonal) hematologic disorder, involving hematopoietic stem cells and characterized by the presence of primitive or atypical myeloid or lymphoid cells in the bone marrow and the blood. "Thus, activation of the ComC in leukemia/lymphoma patients (e.g., as the result of accompanying microbial infections or chemotherapy-induced sterile inflammation) and release of C3 and C5 cleavage fragments could be ameliorated by inhibition of p38 MAPK or upregulation of HO-1." (PMID 31231394, 2019).
listeria infection (2 papers, 2020 to 2025). "Complement C5-deficient A/J mice are hypersusceptible to listeriosis because of severely dampened neutrophil and macrophage responses." (PMID 32453780, 2020).
lung fibrosis (2 papers, 2015 to 2023). "The fibrogenic effect of complement activation in mice seems to occur upstream of C5, as up-regulation of TGF-β does not occur until the later stages of bleomycin-induced pulmonary fibrosis in C5-deficient mice." (PMID 26337158, 2015).
lymphedema (2 papers, 2022 to 2023). Excess fluid collection in tissues, causing swelling. "More cells, including immune cells, accumulated in lymphedema tissues of C3 KO and C5 KO mice than in wild-type mice." (PMID 37940849, 2023). "We also investigated the infiltration of CD4+ T cells in regions of lymphedema of C5 KO mice; the infiltration of CD4+ T cells into the lymphedema region tended to be increased in C5 KO mice, but without statistical significance." (PMID 37940849, 2023). "Activation of the complement pathways was observed in lymphedema tissue, so we compared the extent of lymphedema swelling in C3 KO mice and C5 KO mice with that in wild-type mice." (PMID 37940849, 2023). "The presence of c1, c3, and c5 cells was also confirmed by immunofluorescence staining in the subcutaneous adipose tissue sections from lymphedema patients and healthy donors." (PMID 35725971, 2022). "In the present study, we analyzed whether complement activation is involved in the development of lymphedema using C3 knockout (KO) mice and C5 KO mice." (PMID 37940849, 2023). "Interestingly, more immune cells seemed to infiltrate the lymphedema region in both C3 KO and C5 KO mice compared with in wild-type mice." (PMID 37940849, 2023). "In some C3 KO and C5 KO mice, macrophages and granulocytes were not significantly increased in the lymphedema region, possibly because there was little or no production of C3a and C5a." (PMID 37940849, 2023). "We detected increased infiltration of both F4/80+ macrophage cells and Ly6G+ granulocyte cells into lymphedema tissues of some of C3 KO and C5 KO mice, but the change was not significant." (PMID 37940849, 2023).
multiple sclerosis (2 papers, 2024 to 2025). A progressive autoimmune disorder affecting the central nervous system resulting in demyelination. "Complement system modulation: targeting complement proteins (e.g., C3 and C5 inhibitors) is a promising approach to limit excessive immune activation, particularly in conditions like multiple sclerosis." (PMID 40260075, 2025). "Seven markers were found to be significantly differently expressed in the serum of multiple sclerosis versus controls: osteopontin, Factor B, vitamin D binding protein, C5, iC3b, CRP and neurofilament light." (PMID 38368354, 2024).
nasal polyp (2 papers, 2020 to 2022). "Expression of complement factors, including C3, C5, and the anaphylatoxin receptors, was analyzed in nasal polyp tissue samples, the corresponding inferior turbinates, and healthy controls using transcriptomic methods and protein measurements." (PMID 32724828, 2020).
neuroendocrine pancreatic tumors (2 papers, 2016 to 2017). "The gender bias of pancreatic neuroendocrine tumor metastasis was lost in mice null for the complement C5 gene." (PMID 27105526, 2016). "Complement C5 is a chemoattactant for macrophages, and infiltration of neuroendocrine tumors by CD68+ macrophages has previously been reported to correlate with metastasis both in RT2 mice and in humans with pancreatic neuroendocrine tumors." (PMID 27105526, 2016). "Unfortunately pancreatic neuroendocrine tumor specimens were mostly available only as paraffin sections, and complement C5 antisera were not satisfactory for staining paraffin sections, so it was not possible to run a larger study." (PMID 27105526, 2016).
pneumococcal infection (2 papers, 2017 to 2021). Infections with bacteria of the species streptococcus pneumoniae. "Nevertheless, inhibiting C5 during experimental pneumococcal infection did not affect bacterial killing in vaccinated individuals and only marginally affected it in vaccine-naïve subjects." (PMID 34707606, 2021). "With regard to other immunologic mechanisms protective to pneumococcal infection such as complement-dependent bacterial killing and chemotactic phagocyte attraction, we could not find indication for enhanced C5 activation or macrophage and neutrophil recruitment in SPC-HAxTCR-HA mice." (PMID 28694492, 2017).
pneumonia (2 papers, 2020 to 2023). An acute, acute and chronic, or chronic inflammation focally or diffusely affecting the lung parenchyma, caused by an infection in one or both of the lungs (by bacteria, viruses, fungi, or mycoplasma.). "The complement components, C3a, C5a, and C5, were significantly elevated in all severities of COVID-19-infected patients (mild, moderate, and severe) with pneumonia compared to healthy controls." (PMID 37731491, 2023).
preeclampsia (2 papers, 2014 to 2025). Preeclampsia is a hypertensive disorder of pregnancy that is characterized by new-onset hypertension with proteinuria presenting after 20 weeks of gestation, and depending on mild or severe forms may initially present with severe headache, visual disturbances, and hyperreflexia. "Genetic analyses identify rare variants in complement regulators (CFH, CFI, MCP) and proteins (C5, C6), suggesting a shared mechanism between preeclampsia and complement-mediated disorders like atypical hemolytic uremic syndrome (aHUS)." (PMID 40777009, 2025). "Therapeutically, complement inhibitors like eculizumab, a C5 blocker, show promise in case reports for severe preeclampsia and HELLP, prolonging pregnancy by reducing C5b-9 deposition." (PMID 40777009, 2025).
prion disease (2 papers, 2018 to 2021). A transmissible disease that is caused by a protein that is able to induce abnormal folding of normal cellular proteins, leading to characteristic spongiform brain changes, which are associated with neuronal loss without an inflammatory response. "Though complement components C3 and C5 are not required for prion pathogenesis, the G protein-coupled receptors C3aR1 and C5aR1 might influence prion disease by interacting with other unidentified ligands to elicit a response." (PMID 30596651, 2018). "Surprisingly, deletion of C5, the protein that is cleaved to generate C5a, does not affect scrapie survival or vacuolation, and our results indicate deletion of the C5a receptor C5ar1 also has no measurable effect on prion disease." (PMID 30596651, 2018). "For example, inhibiting the down-stream of complement cascade (C5 and MAC) and/or C5aR could protect the brain from Plasmodium infection-induced tissue damage, whereas inhibition restricted to the upstream components (C1q, C2, and FB) could be beneficial in prion diseases, as shown in animal models." (PMID 34408631, 2021).
steatosis (2 papers, 2016 to 2022). Increased lipid within the cytoplasm of cells. "Anti-C5 treatment did not affect liver histology as the levels of steatosis (52 ± 3%) (macrovesicular (27 ± 2%) and microvesicular (26 ± 3%)) and lobular inflammation 3.1 ± 1.3 inflammatory aggregates/mm2) were all comparable to HFD+vehicle." (PMID 36142647, 2022).
synucleinopathies (2 papers, 2021 to 2022). "Our demonstration of targeting C3 and C5 with CP20 and RaCl is protective in our cell model against α-syn-dependent complement-mediated cytotoxicity supports complement targeting disease-modifying strategies also may hold potential in PD and other synucleinopathies." (PMID 34399786, 2021).
thymoma (2 papers, 2024 to 2025). A neoplasm arising from the epithelial cells of the thymus. "There were also differences in the expression of HLA-A, C5, and SELL (p < 0.05), consistent with the results of the total sample, but due to the small sample size after stratification, more samples of thymoma with different pathological types will be needed in the future for further verification." (PMID 40599774, 2025).
tuberculosis (2 papers, 2014 to 2019). A chronic, recurrent infection caused by the bacterium Mycobacterium tuberculosis. "Complement functions as an important host defense system and complement C5 and C7 have been implicated in immunopathology of tuberculosis." (PMID 24647646, 2014).